DUSP2 (dual specificity phosphatase 2)
Diseases named in the same sentence as DUSP2 in open-access papers (continued):
Sharing a sentence is not in itself a finding about the gene and the disease.
multiple myeloma (2 papers, 2024 to 2025). "In particular, RGS‐1, DUSP2, and CMC1 are associated with immunosuppression and exhaustion as shown in CD8+ T cells of patients with rapidly progressive multiple myeloma." (PMID 39777847, 2025).
non-Hodgkin lymphoma (2 papers, 2016 to 2019). Distinct from Hodgkin lymphoma both morphologically and biologically, non-Hodgkin lymphoma (NHL) is characterized by the absence of Reed-Sternberg cells, can occur at any age, and usually presents as a localized or generalized lymphadenopathy associated with fever and weight loss. "In two-hundred and forty-four follicular lymphoma (FL) cases recognized during a population-based case-control study of non-Hodgkin lymphoma (NHL), five genes (GALNT12,BMP7, DUSP2,GADD45B, andADAM17) were found associated with the overall survival of FL and control of B-cell activity." (PMID 27322213, 2016).
Obesity (2 papers, 2014 to 2023). Accumulation of substantial excess body fat. "To investigate the role of DUSP2 in the context of obesity-associated inflammation and insulin resistance, we exploited a mutant strain of mice that lack DUSP2." (PMID 25375135, 2014). "Given the importance of inflammation and the accumulation of numerous immune cell types in the WAT of obese mice, we hypothesized that a loss of DUSP2 function might reduce obesity-associated macrophage recruitment or inflammation in WAT." (PMID 25375135, 2014). "We hypothesized that a loss of DUSP2 function would reduce obesity-associated inflammation and, consequently, would improve insulin sensitivity in mice fed a HFD." (PMID 25375135, 2014). "In contrast to the previously ascribed role for DUSP2 regulating inflammatory responses in culture and in vivo, our findings reported here demonstrate that DUSP2 plays no role in the development of obesity or obesity-associated inflammation." (PMID 25375135, 2014). "In conclusion, DUSP2 plays no role in regulating obesity-associated inflammation and only a minor role in controlling insulin sensitivity following HFD in female, but not male, mice." (PMID 25375135, 2014). "Our data provide compelling evidence that DUSP2 does not play a non-redundant role in the development of obesity or obesity-associated inflammation and its related pathologies, despite these conditions being underpinned by a strong inflammatory component." (PMID 25375135, 2014). "Studies reporting roles for the MAPK dual specificity phosphatases DUSP1 and DUSP9 during inflammation, obesity and insulin sensitivity, prompted us to investigate what function DUSP2 might play in these processes." (PMID 25375135, 2014). "The absence of DUSP2 can protect mice against obesity-associated inflammation." (PMID 37446885, 2023). "Therefore, it is possible that the low-grade inflammation associated with obesity is not a sufficiently strong stimulus to employ DUSP2 as a means of modulating MAPK dependent inflammatory responses." (PMID 25375135, 2014). "While the absence of DUSP2 had no impact on obesity-associated inflammation and insulin resistance in male mice, we did observe a small, but significant improvement in the insulin sensitivity of female DUSP2-deficient mice fed the HFD." (PMID 25375135, 2014). "We hypothesised that the absence of DUSP2 would protect mice against obesity-associated inflammation and insulin resistance." (PMID 25375135, 2014). "Furthermore, a lack of DUSP2 activity does not prevent the development of obesity-associated glucose intolerance or insulin resistance in male mice, although it does appear to have a small protective effect in female mice." (PMID 25375135, 2014). "Of note, this improvement occurred irrespective of the absence of DUSP2 having no impact on HFD-induced obesity, immune cell recruitment or inflammation in the WAT." (PMID 25375135, 2014). "DUSP2, a nuclear specific DUSP that is mainly expressed in immune cells, had been shown in macrophages and mast cells to promote the production of various inflammatory mediators that included key mediators of obesity-induced metabolic disease." (PMID 25375135, 2014). "Based on these properties of DUSP2, we examined whether obesity driven inflammation in WAT and its associated impact on glucose intolerance and insulin resistance would be reduced in mice lacking DUSP2." (PMID 25375135, 2014). "Functional redundancy amongst the nuclear specific DUSPs, which in addition to DUSP2 include DUSP1, DUSP4 and DUSP5, may also be a contributing factor in DUSP2 not playing a unique role in obesity-associated WAT inflammation." (PMID 25375135, 2014).
rheumatoid arthritis (2 papers, 2014 to 2021). A chronic, systemic autoimmune disorder characterized by inflammation in the synovial membranes and articular surfaces. "Given its pro-inflammatory role in a murine model of rheumatoid arthritis, DUSP2 may positively regulate inflammatory responses also in intestinal immune cells." (PMID 24841635, 2014). "Some studies reported that DUSP1, DUSP2, and DUSP5 are involved in osteoclast-related diseases, such as osteoporosis and rheumatoid arthritis, but the role of DUSP6 has not been studied." (PMID 34475393, 2021).
Sepsis (2 papers, 2024). Sepsis is defined as life-threatening organ dysfunction caused by a dysregulated host response to infection. "Among the upregulated DEGs in E-SEP compared to Y-SEP, we observed inflammation-associated genes, such as FOSB, DUSP1, and JUNB, and aging-associated genes, such as IFN-stimulated genes DDIT4 and DUSP2, thereby indicating an overactive inflammatory response of cDCs in elderly patients with sepsis." (PMID 38909272, 2024). "Collectively, these results pinpoint NFKBIA, NFKB2, TNFSF14, DUSP2, and PIK3C2B as key mediators of DcR3’s broad-spectrum effects in CLP-induced sepsis." (PMID 38700314, 2024).
acute leukemia (1 paper, 2016). A clonal (malignant) hematopoietic disorder with an acute onset, affecting the bone marrow and the peripheral blood. "Downregulation of DUSP2 was detected in human acute leukemia coupled with activation of MEK and hyperexpression of ERK." (PMID 26833217, 2016).
adrenocortical carcinoma (1 paper, 2025). "In our pan-cancer correlation analysis we found significant negative correlations of miR-29 cluster members with DUSP2 expression in various cancer types such as adrenocortical carcinoma, bladder, colorectal and kidney cancer, mesothelioma and uveal melanoma, but most prominent in thymoma." (PMID 40537745, 2025).
atherosclerosis (1 paper, 2022). A disease characterized by the build-up of fatty material and calcium deposition in the arterial wall resulting in partial or complete occlusion of the arterial lumen. "In addition to CCL3, CCL4, and DUSP2, IL1B, known to be highly relevant in atherosclerosis, was highly upregulated in CM of HIV+CVD+ women." (PMID 36045343, 2022).
autoimmune thyroid disease (1 paper, 2025). Inflammatory disease of the thyroid gland due to autoimmune responses leading to lymphocytic infiltration of the gland. "Increased IL-10 expression has been reported in autoimmune thyroid diseases, suggesting that anti-inflammatory responses may occur simultaneously via IL10RB, DUSP1, DUSP2, and RGS1 in GD." (PMID 40710355, 2025).
CNS lymphoma (1 paper, 2024). "Gene alterations in BTG2, PIM1, DUSP2, ETV6 and CXCR4 had been identified in more than 20% of patients with primary CNS lymphoma (PCNSL) in a study by Wang and colleagues." (PMID 38173015, 2024).
colitis (1 paper, 2020). Inflammation of the colon. "DUSP2 inhibition in mice leads to susceptibility to colitis and inflammation and increase secretion of cytokines from TH17 cells." (PMID 32970748, 2020).
colorectal cancer (1 paper, 2018). A primary or metastatic malignant neoplasm that affects the colon or rectum. "However, little is known about the clinical significance of DUSP2 in colorectal cancer (CRC)." (PMID 29540997, 2018).
COVID-19 (1 paper, 2023). A disease caused by infection with severe acute respiratory syndrome coronavirus 2. "However, some studies demonstrated that these NK cells overexpressed several markers related to a dysfunctional phenotype in severe COVID-19, like CD39, PD-1, NKG2A, DUSP2, CD69, CD38, LAG-3 and TIM-3." (PMID 37311004, 2023).
delirium (1 paper, 2025). A disorder characterized by confusion; inattentiveness; disorientation; illusions; hallucinations; agitation; and in some instances autonomic nervous system overactivity. "Novel associations with delirium included transcripts related to stress granule assembly and the T cell regulators DUSP2 and KLF10." (PMID 40982210, 2025).
depression (1 paper, 2020). "For instance, DUSP2 has previously been identified to link stress experience and depression pathogenesis: DUSP1 and DUSP2 expression was increased in response to chronic stress in rodents and in the brain of two separate cohorts of depressed patients." (PMID 32839428, 2020).
dyslipidemia (1 paper, 2015). "Remarkably, in dyslipidemia, there was a reduction in the expression of inflammatory genes (e.g. ATF3, DUSP2 and PTGS2)." (PMID 26083362, 2015).
glioma (1 paper, 2025). A benign or malignant brain and spinal cord tumor that arises from glial cells (astrocytes, oligodendrocytes, ependymal cells). "Furthermore, we confirmed the interaction of miR-17-5p with DUSP2 3’UTR which was previously reported to be highly expressed and associated with poor prognosis in gliomas and described as efficiently de-coupling other negative regulators of the MAPK pathway." (PMID 40537745, 2025).
ischemia (1 paper, 2019). A hypoperfusion of the BLOOD through an organ or tissue caused by a PATHOLOGIC CONSTRICTION or obstruction of its BLOOD VESSELS, or an absence of BLOOD CIRCULATION. "There are also a few studies on DUSP2 in the central nervous system, for example it has been reported that Dusp2 mRNA expression is increased in forebrain neurons resistant to ischemia, but not in the vulnerable neurons, suggesting that DUSP2 may be protecting against this type of stress." (PMID 31293510, 2019).
lymph node metastases (1 paper, 2023). "Results revealed that decreased DUSP2 expression was associated with a higher T stage, a higher Gleason score, and a higher incidence of lymph node metastases." (PMID 36998469, 2023).
Merkel cell carcinoma (1 paper, 2016). "Here we report a significant tumor-specific hypermethylation of DUSP2 in primary Merkel cell carcinoma (p = 0.05)." (PMID 26833217, 2016). "Especially in primary Merkel cell carcinoma a tumor-specific hypermethylation of DUSP2 was revealed." (PMID 26833217, 2016). "Our data show that DUSP2 is aberrantly methylated in primary Merkel cell cancer and in different human cancer cell lines." (PMID 26833217, 2016). "We analyzed the promoter hypermethylation of DUSP2 in human cancer, including primary Merkel cell carcinoma by bisulfite restriction analysis and pyrosequencing." (PMID 26833217, 2016). "Interestingly, 10 out of 22 (45 %) Merkel cell carcinoma showed a DUSP2 hypermethylation." (PMID 26833217, 2016).
pancreatic adenocarcinoma (1 paper, 2021). "Conversely, the expression levels of CCND1, DUSP2, ETS2, JUN, and RALGDS were decreased in lung and pancreatic adenocarcinomas with KRAS mutations." (PMID 33982211, 2021).
Parkinson disease (1 paper, 2023). A progressive degenerative disorder of the central nervous system characterized by loss of dopamine producing neurons in the substantia nigra and the presence of Lewy bodies in the substantia nigra and locus coeruleus. "It was suggested that LPS significantly increased DUSP2 expression but caused a decrease in the p-eIF2a/eIF2a ratio, which was reversed by salubrinal in the LPS-induced intraneural hemi-Parkinson disease (PD) model." (PMID 37208441, 2023).
psoriasis (1 paper, 2022). An autoimmune condition characterized by red, well-delineated plaques with silvery scales that are usually on the extensor surfaces and scalp. "In keratinocytes, previous studies have shown that the expression of DUSP2 and DUSP5 changed in response to an adalimumab treatment in psoriasis patients whereas arsenic, a human carcinogen that can cause squamous cell carcinomas (SCCs), could inhibit the expression of DUSP2 or DUSP14." (PMID 36080217, 2022).
renal fibrosis (1 paper, 2022). A final common manifestation of a wide variety of chronic kidney diseases characterized by glomerulosclerosis and tubulointerstitial fibrosis. "In contrast to the NC mice, the renal injury and inflammation as well as interstitial fibrosis were dramatically alleviated after AAV9-Dusp2 treatment, suggesting that DUSP2 could protect kidney against renal fibrosis post-AKI." (PMID 35836796, 2022).
serous ovarian carcinoma (1 paper, 2011). "Overexpression of DUSP2 expression was found in 37 of 39 malignant effusions from serous ovarian carcinoma patients and was associated with poor survival." (PMID 22118688, 2011).
skin cancer (1 paper, 2016). "Here we show that the promoter of DUSP2 is hypermethylated in different human cancer cell lines including lung, breast and skin cancers and in HEK293 cells." (PMID 26833217, 2016).
spinocerebellar ataxia type 1 (1 paper, 2017). Spinocerebellar ataxia type 1 (SCA1) is a subtype of type I autosomal dominant cerebellar ataxia (ADCA type I) characterized by dysarthria, writing difficulties, limb ataxia, and commonly nystagmus and saccadic abnormalities. "For instance, the individual association of DUSP2, DUSP 4, DUSP 6, DUSP 8, DUSP 11, DUSP 13, DUSP 24 has been reported with ataxin-1, which is the causative protein of spinocerebellar ataxia type 1." (PMID 28902166, 2017).
thymoma (1 paper, 2025). A neoplasm arising from the epithelial cells of the thymus. "Furthermore, we found several members of the large C19MC microRNA cluster to be significantly negatively correlated to DUSP2 expression, exclusively in thymomas." (PMID 40537745, 2025).
cancer (31 papers, 2011 to 2025). A tumor composed of atypical neoplastic, often pleomorphic cells that invade other tissues. "Therefore, the aim of the current study was to determine whether DUSP2 mRNA is a target of cancer-associated microRNAs thereby contributing to the dysregulation of DUSP2 which may occur in specific cancer types." (PMID 40537745, 2025). "A combination of in silico target prediction, integrative analysis of pan-cancer microRNA and DUSP2 mRNA expression data as well as a literature search was applied to identify microRNAs potentially regulating DUSP2 expression in cancer context." (PMID 40537745, 2025). "The next step aimed to identify those of the 83 microRNAs being most likely involved in DUSP2 regulation in cancer context." (PMID 40537745, 2025). "For this purpose, microRNA and DUSP2 expression levels were examined in silico in approximately 9,000 tumour samples of 32 cancer types from the Cancer Genome Atlas (TCGA) program." (PMID 40537745, 2025). "Emerging studies have suggested that DUSP2 served as a favorable factor for cancer metastasis, chemoresistance, and cancer stemness." (PMID 41169612, 2025). "Together with the significant negative correlations between DUSP2 mRNA and abundance of phosphorylated MAPK proteins determined by RPPA observed in several tumour types, these data supported a potential microRNA-mediated DUSP2 regulation in cancer." (PMID 40537745, 2025). "The aim of the present study was therefore to investigate potential microRNA-mediated DUSP2 regulation in cancer, as DUSP2 has recently being identified as microRNA target known to be widely dysregulated in cancer and to contribute to tumorigeneses." (PMID 40537745, 2025). "This link is supported by studies reporting low expression levels of DUSP2 in a range of cancers, including acute leukaemia, breast, colon, lung, ovary, kidney, prostate and cervical cancer." (PMID 40537745, 2025). "With the assistance of RALY, PTBP1 can bind to the pre‐mRNA of DNMT3B and drive an oncogenic splicing switch in DNMT3B to produce DNMT3B‐L, which in turn induces promoter methylation of DUSP2, thereby increasing resistance of cancer cells to irradiation." (PMID 39287090, 2024). "Hypoxia stress can decrease the expression of DUSP2 and increase cancer stemness and tumor growth in CC cells." (PMID 36925652, 2023). "To reveal the epigenetic status of DUSP2 in human cancers in more detail, we have analyzed the methylation of its promoter in several human cancer cell lines by COBRA and by pyrosequencing." (PMID 26833217, 2016). "To further analyze the impact of epigenetic regulation of DUSP2 in carcinogenesis we investigated its expression in normal tissues and cancer cell lines." (PMID 26833217, 2016). "In the present study we have investigated the epigenetic regulation of DUSP2 in detail and we show that DUSP2 is epigenetically silenced by promoter methylation in human cancer." (PMID 26833217, 2016). "Here we analyzed the epigenetic inactivation and regulation of the dual specificity phosphate 2 (DUSP2) in human cancers." (PMID 26833217, 2016). "In summary, 17 out of 24 (71 %) human cancer cell lines exhibited increased DUSP2 promoter methylation." (PMID 26833217, 2016). "Downregulation of the negative regulator DUSP2 of the oncogenic MAPK signaling pathway has been reported in cancer." (PMID 26833217, 2016). "In this study we demonstrate that hypoxia decreases DUSP2 levels in three cancer cell lines and this correlates with increased ERK activation." (PMID 25596742, 2015). "Recently, it has been reported that DUSP2 is downregulated in many cancers and that hypoxic tumors have decrease expression of DUSP2." (PMID 25596742, 2015). "Indeed, Zou and colleagues demonstrated both in vitro and in vivo that the overexpression of DUSP2 suppresses cancer progression through the inhibition of ERK1/2 phosphorylation and M2 macrophages chemotaxis." (PMID 40943262, 2025).